MSI1 (musashi RNA binding protein 1)
Diseases named in the same sentence as MSI1 in open-access papers (continued):
Sharing a sentence is not in itself a finding about the gene and the disease.
brain cancer (4 papers, 2017 to 2022). A primary or metastatic malignant neoplasm affecting the brain. "To facilitate a large-scale comparative study of MSI1 function and targetability in childhood brain cancer, we investigate its role as a mediator of stemness in neural stem cells by comparison with BTICs from endogenously MSI1-enriched MYC-amplified G3 MB." (PMID 36473869, 2022). "The identification of MSI1–directed inhibitors such as Luteolin could thus represent a promising strategy to sensitize brain cancer cells for chemo– or radiotherapy." (PMID 34062997, 2021). "The expression and role of MSI1 in cancer was predominantly studied in brain cancers." (PMID 34062997, 2021).
breast tumor (4 papers, 2010 to 2023). "In breast tumors, a bimodaldistribution of Msi1 expression was observed, with a roughly evensplit between up- and down-regulation of Msi1, consistent with theidea that Msi1 upregulation might be specific to a subtype of breasttumors." (PMID 25380226, 2014). "Similarly, QKI (Quaking) is downregulated in different breast tumor subtypes (RBM38 ER, PR, and HER2 positive, non-basal-like, and non-TNBC) while PCBP2 (Poly (C) binding protein 2), HuR (Hu-antigen R), LIN28, SAM68, and MSI-1 and -2 (Musashi-1 and -2) are upregulated." (PMID 37176013, 2023).
leukemia (4 papers, 2013 to 2021). A malignant (clonal) hematologic disorder, involving hematopoietic stem cells and characterized by the presence of primitive or atypical myeloid or lymphoid cells in the bone marrow and the blood. "Recently, Msi1 and Msi2 were found to be overexpressed in tumors of various organs and in leukemias." (PMID 28753936, 2017). "Additionally, increased expression of Msi1 and Msi2 has been found in leukemias such as acute myelogenous leukemia and acute lymphoblastic leukemia." (PMID 28753936, 2017). "Recent studies suggest that the translation of NUMB mRNA, which is a known target of MSI1, inversely correlates with MSI2 expression in leukemia." (PMID 23667531, 2013).
microcephaly (4 papers, 2019 to 2024). A congenital or acquired developmental disorder in which the circumference of the head is smaller than normal for the person's age and sex. "MSI1 plays a particularly important role in brain development, and increased expression of Musashi proteins in patients infected with Zika virus during pregnancy has been associated with microcephaly." (PMID 35840700, 2022). "Indeed, MSI1 is necessary in neurodevelopment for both vertebrates and invertebrates in which microcephaly is exhibited by MSI1-depleted zebrafish and mutant mice displaying thin cerebral cortex besides other morphological brain abnormalities." (PMID 31824472, 2019). "The concomitant finding that Msi1 is mutated in individuals with autosomal recessive primary microcephaly suggested the following working model: because of binding of Msi1 to ZIKV RNA, ZIKV infection could induce microcephaly by titrating Msi1 protein." (PMID 34916907, 2021).
retinoblastoma (4 papers, 2007 to 2019). A malignant tumor that originates in the nuclear layer of the retina. "SD±0.55) and Y79 (1.21%, SD±0.49) contained nuclear β-catenin in both cell lines (p<0.001 compared with Msi1-positive cells, n=5), indicating that retinoblastoma cells with active Wnt signaling were more likely to be stem cells." (PMID 20069066, 2010).
acute myeloid leukemia (3 papers, 2012 to 2019). Acute myeloid leukemia (AML) is a group of neoplasms arising from precursor cells committed to the myeloid cell-line differentiation. "The MUSASHI (MSI) family of RNA binding proteins (MSI1 and MSI2) contribute to a wide spectrum of cancers including acute myeloid leukemia." (PMID 31217428, 2019).
bladder carcinoma (3 papers, 2015 to 2021). "MSI1 is up-regulated as SGs component in bladder carcinoma cell lines relative to normal uroepithelial cells and inhibits apoptosis by targeting mRNA of essential genes, including P21 CIP1." (PMID 34604242, 2021).
lymph node metastasis (3 papers, 2010 to 2025). "In the case of lymph node metastasis, the levels of MSI1 mRNA expression were higher than the EGFR expression in tumors with metastatic lymph nodes (1.02 ± 0.46 vs. 0.61 ± 0.47, fold changes)." (PMID 30202417, 2018). "Msi1 was expressed in 68% of primary tumors and in 100% of lymph node metastases, and correlated with 5 year survival." (PMID 20727204, 2010). "A recent study found an exceptionally high co‐expression rate of HER2 and the RNA‐binding protein MSI1 in MPD, with MSI1 expression positively correlating with lymph node metastasis." (PMID 41368065, 2025).
myeloid leukemia (3 papers, 2017 to 2022). A clonal proliferation of myeloid cells and their precursors in the bone marrow, peripheral blood, and spleen. "It is also important to note that Ro inhibits both MSI1 and MSI2 and although MSI1 is expressed at low levels in myeloid leukemia it could still be blocking residual MSI1 activity." (PMID 31217428, 2019). "Upregulation of both Musashi homologues MSI1 and MSI2 has been reported in numerous neoplasms, including aggressive myeloid leukemia." (PMID 35528200, 2022).
pancreatic cancer (3 papers, 2016 to 2024). "Of particular interest was the fact that targeting MSI1 expression inhibited pancreatic cancer growth in a human cell line and in a patient-derived xenograft in vivo." (PMID 39682684, 2024). "For instance, MSI1 and MSI2 were found to be potentially “druggable” by antisense oligonucleotides in a human pancreatic cancer line and a pancreatic cancer mouse model." (PMID 39682684, 2024).
ZIKV infection (3 papers, 2018 to 2023). "Furthermore, knockdown of MSI1 in hNPCs significantly down-regulated ZIKV E protein expression as well as viral RNA amounts after WT ZIKV infection, whereas there was no impact on the growth of pMBS1m." (PMID 36854751, 2023).
adenoma (2 papers, 2013 to 2021). A neoplasm arising from the epithelium. "To this aim we studied the expression of LGR-5, MSI-1, DCAMKL-1, CD133 and ALDH1-A1 in normal mucosa, in MDF (microscopic precancerous lesions) and in macroscopic tumours (adenomas) of DMH-induced rats using immunohistochemistry." (PMID 23374535, 2013).
Alzheimer disease (2 papers, 2020 to 2021). A progressive, neurodegenerative disease characterized by loss of function and death of nerve cells in several areas of the brain leading to loss of cognitive function such as memory and language. "Here, we investigated the expression and cellular localization of MSI1 and MSI2 in the brains tissues of Alzheimer’s disease (AD), amyotrophic lateral sclerosis (ALS) and frontotemporal dementia (FTD) as well as in the wild-type mice and tau knock-out and P301L tau mouse models." (PMID 32855391, 2020).
Arthritis (2 papers, 2015 to 2021). Inflammation of a joint. "A role of MSI1 has been previously suggested in bone repair by demonstrating an increased detection in articular joints under repair after induction of arthritis." (PMID 33810326, 2021). "The objectives of this study were to morphologically analyze the experimental collagen-induced arthritis model, to evaluate the effect of treatment with a TNFα-blocker (etanercept), and to determine the immunohistochemical expression of Msi1 protein." (PMID 26064941, 2015).
colorectal tumors (2 papers, 2011 to 2014). "MSI1 depletion in medulloblastoma and colorectal tumors results in decreased proliferation and increased apoptosis." (PMID 24935936, 2014). "In colorectal tumors, MSI1 depletion is accompanied by inhibition of Notch-1 and upregulation of p21WAF1, a MSI1 target involved in cell cycle regulation." (PMID 24935936, 2014).
esophageal squamous cell carcinoma (2 papers, 2021). Esophageal squamous cell carcinoma (ESCC) is a type of esophageal carcinoma (EC) that can affect any part of the esophagus, but is usually located in the upper or middle third. "Meysam’s study showed Msi1 is an important activator for Wnt pathways in esophageal squamous cell carcinoma progression and metastasis." (PMID 33776902, 2021).
frontotemporal dementia (2 papers, 2020 to 2021). Frontotemporal dementia (FTD) comprises a group of neurodegenerative disorders, characterized by progressive changes in behavior, executive dysfunction and language impairment, as a result of degeneration of the medial prefrontal and frontoinsular cortices. "Despite ectopic MSI1 in AD and Pick’s Disease being reported many years ago14, nothing has been found out about its pathogenesis until now." (PMID 32855391, 2020).
malignant glioma (2 papers, 2016 to 2024). A grade III or grade IV glioma arising from the central nervous system. "To explore the potential targets involving in MSI1-driven tumor-resistance in malignant glioma, we sought to in silico analyze the global gene expression profile to explore the impact of MSI1 overexpression in GBM cells." (PMID 27285760, 2016). "MSI1, a homologous protein of MSI2, has been reported to regulate radiation‐induced DNA damage by promoting non‐homologous end joining in malignant gliomas, and inhibition of MSI1 increases radiosensitivity of malignant gliomas." (PMID 38645664, 2024).
mesothelioma (2 papers, 2013 to 2021). A usually malignant and aggressive neoplasm of the mesothelium which is often associated with exposure to asbestos. "We determined that MSI2 is more abundantly expressed compared to MSI1 in mesothelioma and mesothelial cells." (PMID 34944051, 2021).
metastatic disease (2 papers, 2010 to 2013). "When Msi1 detection was combined with histopathological examination, the percentage of positive diagnoses was increased from 81% to 100% (results not shown), and the higher expression of Msi1 in metastatic disease may further increase its value as a diagnostic marker." (PMID 23715514, 2013).
neuroblastoma (2 papers, 2015 to 2023). Neuroblastoma (NB) is the most common solid, extracranial childhood tumor. "This was associated with elevated expression of neuroblastoma (e.g. Phox2b), sympatho-adrenal (e.g. Th), neural (e.g. Gap43), neural stem cell (e.g. Msi1) and neural crest cell markers (e.g. Tfap2b)." (PMID 37246217, 2023).
squamous cell carcinoma (2 papers, 2013 to 2023). A carcinoma arising from squamous epithelial cells. "Msi1 was expressed in a diffuse pattern in most tumor subtypes, except in squamous cell carcinomas, where it appeared in a focal pattern in 50% of specimens." (PMID 23715514, 2013). "Functional studies in A549 bronchioalveolar carcinoma and NCI-H520 squamous cell carcinoma cells revealed that Msi1 was enriched in spheroid cultures of tumor cells and in the CD133+ cell population." (PMID 23715514, 2013). "With the exception of squamous cell carcinomas, ≥50% of tumors expressed Msi1 in a diffuse pattern." (PMID 23715514, 2013).
triple-negative breast carcinoma (2 papers, 2015 to 2025). An invasive breast carcinoma which is negative for expression of estrogen receptor (ER), progesterone receptor (PR), and human epidermal growth factor receptor 2 (HER2). "In addition, we studied CD44 and MSI1, which have been reported to have promoter hypomethylation in triple-negative breast cancers, that is, cancers that lack estrogen receptors (ER), progesterone receptors (PR), and human epidermal growth factor-2 receptors (HER2)." (PMID 26510686, 2015).
anemia (1 paper, 2021). A reduction in the number of red blood cells, the amount of hemoglobin, and/or the volume of packed red blood cells. "KEGG: Fanconi_anemia and KEGG: Signaling_pathways_regulating_pluripotency_of_stem_cells also showed a strongly conserved association with MSI1 in ca. 45% of all 18 tumor types and 3 out of the top four MSI1 related cancers." (PMID 34062997, 2021).
cervical (1 paper, 2014). "As far as we know, this is the first paper to demonstrate that Msi1 is a tumor enhancer in cervical carcinogenesis." (PMID 25362645, 2014).
cognitive decline (1 paper, 2023). "To investigate the potential beneficial effect of msi-1 inhibition on age-dependent cognitive decline, we compared LTAM in 1- and 2-day-old wild-type and msi-1 (lf) worms." (PMID 36378468, 2023).
colon adenocarcinoma (1 paper, 2021). "Additionally, it was revealed that MSI1 absence facilitated cell apoptosis in colon adenocarcinoma." (PMID 33882945, 2021).
Constipation (1 paper, 2017). Infrequent or difficult evacuation of feces. "The densities of Msi-1, NEUROG3, CgA, and serotonin cells were reduced in all IBS patients and in patients with diarrhea-predominant IBS (IBS-D), mixed-diarrhea-and-constipation IBS (IBS-M), and constipation-predominant (IBS-C) relative to the control subjects." (PMID 28764761, 2017).
cyst (1 paper, 2022). A sac-like closed membranous structure that may be empty or contain fluid or amorphous material. "Since Msi function is abrogated in both germline and soma of msi1/1 mutants, we assayed msi1/M1 transheterozygotes for evidence of cyst collision." (PMID 36371343, 2022). "In about 32% of msi1/1 ovaries (N = 28), germline cysts in region 2a-2b appeared to exhibit a cyst collision phenotype." (PMID 36371343, 2022). "msi1/M1 germaria labelled with Vasa in combination with Fas 3 revealed cyst collisions in 30% (N = 60) of msi1/M1 germaria." (PMID 36371343, 2022). "In msi1/M1 mutants, 9 of the 11 dying cysts in msi1/M1 mutants were in region 2a/b, supporting the hypothesis that msi mutant somatic cells in this region are defective in providing the necessary signals to the germline to fully support germline cyst progression in early oogenesis." (PMID 36371343, 2022).
developmental delay (1 paper, 2024). "The expression levels of other genes associated with developmental delay (FOXG2, NLGN2, and MSI1) peaked later in the lineage." (PMID 39363111, 2024).
E. coli infection (1 paper, 2020). "MSI-1 administration significantly alleviated lung lesion, indicating that MIS-1 could reverse lung injury caused by penicillin-resistant E. coli, indicating that MSI-1 attenuates acute systemic E. coli infection in mice." (PMID 31938070, 2020).
fibroma (1 paper, 2022). A non-metastasizing neoplasm arising from the fibrous tissue. "Simultaneously, elevated expression levels of EGFR, KIAA1199, NF-κB p50, and MSI1 were also confirmed in myelocytomas, fibromas, and lymphomas using WB." (PMID 36291177, 2022).
ganglioglioma (1 paper, 2023). A well differentiated, slow growing neuroepithelial neoplasm composed of neoplastic, mature ganglion cells and neoplastic glial cells. "Co-expression of CD34, PAX6, SOX2, and MSI1 (after stringent counter selection against vascular cells using PECAM1, VWF, DCN, and COL1A2), was particularly strongly associated with ganglioglioma neoplastic cell stemness." (PMID 36966348, 2023).
gynecologic cancers (1 paper, 2022). "Msi-1 has previously been demonstrated to be overexpressed in a wide variety of malignancies, including in brain, gastrointestinal and other gynecologic cancers." (PMID 35619161, 2022).
Infertility (1 paper, 2020). "Although these studies confirmed that MSI1 is a key component of stem cell development and oocyte maturation, understanding the similar function of MSI1 and its role in human fertility and infertility remains to be obscured." (PMID 32448364, 2020).
Kidney tumors (1 paper, 2014). "Furthermore, thesystematic downregulation of Msi1/Msi2 and high frequency ofMsi1 mutations in kidney tumors suggests that kidney would be aninformative model for studying Msi loss-of-function and its consequences in cancer." (PMID 25380226, 2014).
male infertility (1 paper, 2024). The inability of the male to effect fertilization of an ovum after a specified period of unprotected intercourse. "Two transgenic mouse models with germ cell-specific overexpression of MSI1 or MSI2 transcripts showed a significant decrease in the ability of sperm to bind effectively to the zona pellucida of a control mouse oocyte, with MSI2 overexpression resulting in male infertility." (PMID 39285325, 2024).
metastatic colorectal cancer (1 paper, 2021). "In metastatic colorectal cancer, MSI1 expression was enhanced by Notch signaling, suggesting a feed–forward circuit, potentially involving KLF4, which was shown to bind to the MSI1 promotor." (PMID 34062997, 2021).
non-small cell lung carcinoma (1 paper, 2020). A group of at least three distinct histological types of lung cancer, including non-small cell squamous cell carcinoma, adenocarcinoma, and large cell carcinoma. "On the other hand, MSI1 controls carcinoma malignancy and chemoresistance through modifying the activity of the Akt signaling pathway in non-small cell lung carcinoma." (PMID 32448364, 2020). "Recently, it has been shown that MSI1 stimulates glucose uptake in non-small cell lung carcinoma (NSCLC) and influences the mitochondrial respiration and aerobic glycolysis affecting the cell oxygen consumption rate (OCR) and extracellular acidification rate (ECAR) in A549 and H522 cells." (PMID 32448364, 2020). "During studies in non-small cell lung carcinoma, it was demonstrated that MSI1 is regulated by miR-181a-5p and there is a negative correlation between MSI1 and miR-181a-5p expressions in NSCLC patients." (PMID 32448364, 2020).
polyposis (1 paper, 2018). "MSI1 binds to and negatively regulates translation of Numb and APC (adenomatous polyposis coli), negative regulators of Notch and Wnt signaling respectively." (PMID 30097032, 2018).
rectal cancer (1 paper, 2015). A primary or metastatic malignant neoplasm that affects the rectum. "We are the first to report an overexpression of MSI1 specifically in rectal cancer in a large patient cohort." (PMID 25940441, 2015). "MSI1 protein expression was analyzed using immunohistochemistry in distant normal mucosa, adjacent normal mucosa, primary tumor and lymph node metastasis tissue samples collected from patients with rectal cancer." (PMID 25940441, 2015). "Collectively, this suggests that future therapeutic strategies targeting MSI1 may be relevant for both colon and rectal cancer patients and possibly in combination with conventional treatment strategies, such as radiation therapy." (PMID 25940441, 2015).
rectal tumor (1 paper, 2015). "MSI1 protein was found to be highly expressed in 79% of primary rectal tumors (n=146), while miR-137 expression was decreased in 84% of the rectal tumor tissues (n=68) compared to paired normal mucosal samples." (PMID 25940441, 2015). "Additionally, we found that MSI1 protein expression is more abundant in rectal tumors compared to paired adjacent and distant normal mucosa." (PMID 25940441, 2015).
small-intestinal adenomas (1 paper, 2013). "These authors reported that MSI-1 is localized in the stem compartment of the intestinal crypts and is overexpressed in small-intestinal adenomas of the Min mouse, a genetic model of intestinal carcinogenesis." (PMID 23374535, 2013).
viral infection (1 paper, 2025). "Following viral infection, there is a marked increase in MSI1 levels in the cytoplasm, with significant accumulation observed around the perinuclear region, alongside an upregulation of MSI1 expression within the nucleus." (PMID 39936918, 2025).